PINX1 (PIN2 (TERF1) interacting telomerase inhibitor 1)
Diseases named in the same sentence as PINX1 in open-access papers (continued):
Sharing a sentence is not in itself a finding about the gene and the disease.
cancer (33 papers, 2011 to 2025). A tumor composed of atypical neoplastic, often pleomorphic cells that invade other tissues. "Recently, our group discovered that that not only does PinX1 contribute to telomere maintenance, but it also affects cancer cell sensitivity to DNA damage caused by chemo-radiotherapy or chemotherapeutics." (PMID 28978030, 2017). "Furthermore, we demonstrated that PINX1 deficiency leads to susceptibility of cancer cells to PARP inhibitors both in vitro and in vivo, suggesting that its inhibition combined with PARP inhibitors can serve as a potential therapeutic strategy." (PMID 39174499, 2024). "Loss of PinX1 leads to increased telomere length contributing to the development of cancer." (PMID 34337078, 2021). "Owing to severe heterogeneity, subgroup analyses stratified by tumor type, sample size, test method, cutoff value, type of analysis, and NOS score were conducted to investigate the association between PINX1 expression and OS in patients with various types of malignant tumors." (PMID 30079348, 2018). "The pooled results for OS and DFS/RFS showed that low PINX1 expression was associated with poor prognosis, suggesting that PINX1 may function as a tumor suppressor gene in malignant tumors." (PMID 30079348, 2018). "It has been confirmed that PINX1 deficiency could lead to telomerase activation, telomere elongation and chromosome instability, however overexpression of PINX1 caused a decrease in both telomerase activity and cancer cell tumorigenicity." (PMID 29371971, 2017). "Furthermore, our analysis of several human cancers from the cBioportal database revealed more frequent PinX1 homozygous depletion and PinX1 heterozygous deficiency, but both more infrequent PinX1 gain and rare instances of PinX1 amplification." (PMID 28978030, 2017). "Pin2/TRF1 binding protein X1 (PinX1) has been identified as an endogenous telomerase inhibitor and a major haploinsufficient tumor suppressor gene localized at human chromosome 8p23, a region with frequent loss of heterozygosity in a number of human cancers." (PMID 24936151, 2014). "Therefore, PinX1 may be a new potential diagnostic biomarker and therapeutic target for human cancers, and may play different roles in different human cancers." (PMID 27556185, 2016). "Moreover, reducing PinX1 levels by heterozygous knockout or knockdown leads to chromosome instability and tumorigenesis in vitro and in vivo, with most tumors in PinX1+/- mice being carcinomas and sharing tissues of origin with human cancer types linked to 8p23." (PMID 22021332, 2011). "Overexpression of LPTS/PinX1 protein can inhibit the growth of multiple telomerase-positive cancer cell lines." (PMID 40896430, 2025). "Then we investigated the impact of PinX1 on stemness-associated phenotypes and found that telomerase activity was closely correlated with cancer stemness in CESC and even in pan-cancer." (PMID 39634130, 2025). "Complicated functions of PinX1 endow it with a versatile role in cancers, namely inhibiting malignancy in gastric, breast and renal cancer cells, or promoting proliferation in glioblastoma and prostate cancer cells." (PMID 40639785, 2025). "Together, these results indicated that LPTS/PinX1 level is reduced in most human cancer tissues and cells and that LPTS/PinX1 is a major tumor suppressor." (PMID 40896430, 2025). "As a natural suppressor of telomerase, PinX1 represents a potential strategy for curtailing cancer progression by targeting telomerase." (PMID 39634130, 2025). "Collectively, PinX1 shortens telomeres and suppresses cancer stemness in CESC through the inhibition of telomerase activity, and TID with lysine residues clustered in PinX1292-301 are crucial for this suppressive effect." (PMID 39634130, 2025). "In all 11 cancer cell lines, the level of LPTS/PinX1 protein decreased compared with that in the normal liver cell lines L02 and QSG-7701." (PMID 40896430, 2025).
cancer (continued). "Here, we unveil PIN2/TRF1-interacting telomerase inhibitor 1 (PINX1) as an uncharacterized PARP1-interacting protein that synergizes with PARP inhibitors upon its depletion across various cancer cell lines." (PMID 39174499, 2024). "Previous studies have shown a correlation between a decrease in PINX1 expression and the metastatic nature and poor prognosis of cancer patients." (PMID 36142793, 2022). "In the previous study, it has been found that pinX1 overexpression in human cancer cells shortens telomeres, induces crisis, and inhibits tumorigenicity, whereas pinX1 depletion plays the opposite role." (PMID 35847001, 2022). "What is more, in our pre-experiment, we found that hesperidin inhibited cancer cell proliferation with an increase of pinX1 expression." (PMID 35847001, 2022). "p65 can bind to the PINX1 promoter to inhibit PINX1 transcription, which leads to the increased proliferation of cancer cells." (PMID 33549103, 2021). "Six pDGVs in the PINX1, MOB1A, CLTCL1, PRR5, CCDC136, and TRIM32 genes involved the exact amino acid residues affected by known somatic cancer variants." (PMID 33273457, 2020). "PinX1, a tumor suppressor gene, was previously demonstrated to be a powerful tool for targeting telomerase in order to resist malignant tumor proliferation and migration." (PMID 32028978, 2020). "The overexpression of PinX1 would decrease telomerase activity, thus shortening telomeres, and lower cancer cell tumorigenicity." (PMID 31210926, 2019). "To date, no meta-analyses have been conducted to determine the prognostic value of low PINX1 expression in patients with malignant tumors." (PMID 30079348, 2018). "Further eligible studies are needed to determine the prognostic value of PINX1 expression in various types of malignant tumors." (PMID 30079348, 2018). "In this meta-analysis, we showed that low PINX1 expression was associated with significantly poorer OS, DFS/RFS, and clinicopathological characteristics in patients with various types of malignant tumors." (PMID 30079348, 2018). "This is the first meta-analysis to evaluate the prognostic value of PINX1 expression in patients with malignant tumors." (PMID 30079348, 2018). "Many studies have shown that PinX1 can regulate telomere maintenance in cancer cells, ultimately inhibiting telomere elongation." (PMID 28978030, 2017). "Collectively, our data reveal PinX1 expression patterns and potential mechanisms in various human cancers." (PMID 28978030, 2017). "Rather, loss of hetereozygosity seems to play a major role in the inactivation of PinX1 in human cancers." (PMID 28978030, 2017). "Our group recently reported that not only does PinX1 contribute to telomerase activity and cancer tumorigenicity but it also increases the sensitivity of cancer cells to DNA damage and chemo-radiotherapy." (PMID 28372542, 2017). "In other types of cancer, PinX1 expression has been shown to be a predictor of cervical SCC (CSCC) cell response to cisplatin/paclitaxel chemotherapy." (PMID 28815183, 2017). "Previous studies have suggested that PinX1 is an intrinsic telomerase inhibitor and a putative tumour-suppressor gene in human cancers." (PMID 28815183, 2017). "When compared with normal tissue, PinX1 mRNA expression was significantly decreased in most of the selected cancer tissues." (PMID 28978030, 2017). "To verify the PinX1 mRNA expression data found in our analysis of past studies in cBioportal for Cancer Genomic, we selected nine types of primary cancer patients’ tissues from our affiliated hospitals." (PMID 28978030, 2017). "The same study also showed that PinX1 contributes to tumorigenicity in cancer cells, in contrast with other studies." (PMID 28815183, 2017).
cancer (continued). "We thus investigated the genetic profile and biological implication of PinX1 in several human cancers using the cBioportal database." (PMID 28978030, 2017). "Nevertheless, our findings provide important contributions to our understanding of PinX1 function in cancer." (PMID 28815183, 2017). "The expression of PINX1 significantly decreased some human cancers and was correlated to the adverse outcome of cancer patients." (PMID 29371971, 2017). "Given this, further work will be needed to clarify the mechanisms of PinX1 in regulation of tumorigenesis and the progression of different types of human carcinomas." (PMID 28978030, 2017). "As a major tumor suppressor, PinX1 has been demonstrated to be a new potential target in cancer therapy." (PMID 27556185, 2016). "PinX1 can potently inhibit telomerase activation and telomeres elongation in cancer cells, this ability is also conserved in yeast, rats and zebra fish." (PMID 27556185, 2016). "It seems further works are needed to clarify the mechanisms of PinX1 in regulating tumor genesis and progression of different types of human carcinomas in detail." (PMID 27556185, 2016). "Increasing evidence demonstrate that PinX1 plays a key role as a putative tumor suppressor in human cancer progression." (PMID 25888829, 2015). "Twenty-four hours or forty-eight hours after transfection, PinX1 proteins were significantly overexpressed or knockdown in ccRCC cancer cells, respectively." (PMID 26033551, 2015). "Forty-eight or twenty-four hours after transfection, PinX1 protein was significantly knockdown or overexpressed in cancer cells, respectively." (PMID 25888829, 2015). "Then increasing evidences demonstrate that PinX1 plays a key role as a putative tumor suppressor in human cancer progression." (PMID 25888829, 2015). "Increasing evidence suggests that decreased expression of PinX1 plays a key role in different human cancers." (PMID 24672800, 2014). "PinX1 is a conserved nucleolar protein that has complex roles in telomerase/telomere regulation and cancer." (PMID 24940406, 2014). "The inhibition of endogenous PinX1 in human cancer cells increases the telomerase activity and elongates the telomeres, whereas overexpression of PinX1 inhibits telomerase activity and induces cell crisis." (PMID 24672800, 2014). "In humans, ectopic overexpression of PinX1 leads to a decrease in both telomerase activity and cancer cell tumorigenicity, whereas suppression of PinX1 expression results in an increase in both telomerase activity and cancer cell tumorigenicity." (PMID 24268029, 2013). "PinX1 gene is located on chromosome 8p22-23 region, which has high frequency of loss of heterozygosity (LOH) in a series of human cancer cells." (PMID 22316341, 2012). "The significance of these results is demonstrated by our observations that most PinX1+/- mice develop aggressive cancers that display telomere lengthening and chromosome instability." (PMID 22021332, 2011). "Then, we used the LPTS/PinX1+/- mice to study the incidence of cancer in these mice." (PMID 40896430, 2025). "Furthermore, PinX1 deletion significantly correlated with increased cancer stemness and poor prognosis in CESC and even pan-cancer analysis." (PMID 39634130, 2025). "We statistically analyzed the level of LPTS/PinX1 protein in 9 cancer cell lines." (PMID 40896430, 2025). "In this study, we demonstrated that TPCH, which derived from LPTS/PinX1, could inhibit the growth of 11 telomerase-positive tumor cells belonging to 9 kinds of immortal human cancer cell lines in vitro, and 3 types of CDX and 2 types of PDX in vivo." (PMID 40896430, 2025). "LPTS/PinX1, a human liver putative tumor suppressor, could inhibit the cancer cell growth by binding to the hTERT/hTR complex directly." (PMID 40896430, 2025). "However, studies have also demonstrated PINX1’s involvement in promoting tumor progression in various cancers, raising questions about its exclusive role as a telomerase inhibitor or tumor suppressor." (PMID 39174499, 2024).
cancer (continued). "The role of PinX1 in tumorigenesis and progression varies widely among cancer types." (PMID 38431575, 2024). "Differences in the composition of these mechanisms in different cancer cells may also explain the reported paradoxical function of PINX1 in either promoting or inhibiting cancer progression, requiring further research to clarify." (PMID 39174499, 2024). "Similarly, the inhibitory effect of hesperidin on cancer cell invasion and migration can be canceled by pinX1 siRNA." (PMID 35847001, 2022). "An SCC tissue microarray with 86 cancer samples was stained by the pinX1 antibody." (PMID 35847001, 2022). "Similarly, PIN2/TRF1-interacting telomerase inhibitor 1 (PinX1) is involved in the development of cancer through angiogenesis." (PMID 35734237, 2022). "Besides increasing sensitivity to DNA damage in cancer cells, PinX1 was also shown to suppress cell cycle progression." (PMID 31210926, 2019). "In addition, silencing PinX1 expression led to a substantial telomere length shortening and growth inhibition in telomerase-positive human cancer cells." (PMID 31210926, 2019). "However, low PINX1 expression plays various roles in tumor progression and its prognostic value in patients with malignant tumors remains controversial." (PMID 30079348, 2018). "Hence, we conducted a meta-analysis to increase the sample size and to reduce bias in assessing the prognostic value of PINX1 expression in various types of malignant tumors." (PMID 30079348, 2018). "In addition, low PINX1 expression has been shown to affect chemoradiotherapy sensitivity in cancer cells." (PMID 30079348, 2018). "Therefore, we conducted a meta-analysis of 14 studies containing 2,624 patients to determine the prognostic value of PINX1 expression for survival in patients with malignant tumors." (PMID 30079348, 2018). "Therefore, more eligible studies are needed to validate the prognostic value of PINX1 expression in other types of malignant tumors." (PMID 30079348, 2018). "Therefore, we conducted this first meta-analysis to determine the prognostic and clinicopathological value of low PINX1 expression in patients with various types of malignant tumors." (PMID 30079348, 2018). "PinX1 expression was examined using IHC in an NSCLC tissue microarray with 158 cancer samples." (PMID 28815183, 2017). "We then continued our study in vitro to investigate whether knock-down of PinX1 expression promotes cell proliferation in cancer cell lines." (PMID 28978030, 2017). "PinX1 mRNA expression was decreased in most selected cancer tissues, which could promote tumor growth and enhance tumorigenicity." (PMID 28978030, 2017). "Although there is mounting evidence suggesting PinX1’s role in cancer development and progression." (PMID 28372542, 2017). "We also observed that knockdown of PinX1 could also enhance cell proliferation in nine types of cancer cell lines in vitro." (PMID 28978030, 2017). "PinX1 expression is significantly reduced in a variety of cancer types." (PMID 28815183, 2017). "However, cell proliferation in both kidney (HK-2 cell line) and ovarian (SKOV3 cell line) cancer cells transfected with PinX1 siRNA had significantly increased proliferation until 36 h after transfection (P<0.05)." (PMID 28978030, 2017). "Our results indicated that PinX1 deletion is a common genotype in human cancer patients, leading us to believe that insufficient PinX1 may be involved in the progression of a variety of human cancers." (PMID 28978030, 2017). "Moreover, it has been demonstrated that PinX1 is a major haplo-insufficient tumor suppressor gene, stemming from its correlation with chromosome instability and cancer initiation." (PMID 28372542, 2017). "Finally, we selected nine types of cancer samples from our affiliated hospitals to verify their respective PinX1 mRNA expression status." (PMID 28978030, 2017). "PinX1 expression status has been shown to be altered in many cancers." (PMID 28815183, 2017).
cancer (continued). "Then, increasing evidence demonstrate that PinX1 plays a key role in cancer progression." (PMID 27556185, 2016). "The mechanism of PinX1 function in human cancer cells has yet to be fully elucidated." (PMID 27556185, 2016). "The functions and the mechanisms of PinX1 in various human cancers remain unclear, suggesting the necessity of further extensive works of its role in tumor genesis and progression." (PMID 27556185, 2016). "Moreover, the role of PinX1 as a putative tumor suppressor was proved by several other groups in different cancer cell lines, such as human breast cancer cells, hepatoma cells, burkitt's lymphoma cells and esophageal epithelial cells." (PMID 26033551, 2015). "Increasing evidence demonstrate that reduced expression of PinX1 promotes cancer progression and propose that PinX1 may be an attractive therapeutic target for human cancers." (PMID 26033551, 2015). "It has been identified that Pinx1 deficiency could induce telomerase activation, telomere elongation and chromosome instability, whereas overexpression of PinX1 leads to a decrease in both telomerase activity and cancer cell tumorigenicity." (PMID 25888829, 2015). "Then, increasing evidence demonstrated that PinX1 plays a key role in cancer progression." (PMID 26033551, 2015). "Two sided Fisher's exact analysis revealed that PinX1 expression in the carcinoma tissues of the training cohort conspicuously correlated with some clinicopathological features, such as depth of invasion-pT status (P = 0.018), lymph node metastasis-pN status (P = 0.043), and TNM stage (P = 0.013)." (PMID 26033551, 2015). "PinX1 knockout in mice can result in embryonic lethality in the PinX1 null mice (PinX1−/−) and the spontaneous development of a variety of malignant tumors in the PinX1 knockout heterozygous mice (PinX1+/−), indicating that PinX1 is a potent telomerase inhibitor and a putative tumor suppressor." (PMID 24672800, 2014). "Moreover, the role of PinX1 as a putative tumor suppressor was proved by several other groups in different cancer cell lines." (PMID 24936151, 2014). "Disruption of the PinX1-dependent telomere maintenance pathway could reduce carcinogenesis and enhance chemotherapeutic sensitivity in telomerase-positive human cancer cells as well." (PMID 24268029, 2013). "It has been proposed that the PinX1 gene could be a putative tumor suppressor gene and/or therapeutic target for human cancers." (PMID 24268029, 2013). "Subsequent PinX1 studies on human cancer samples are inconclusive." (PMID 22021332, 2011). "Importantly, PinX1+/- cancer cells also display chromosome instability, similar to those in PinX1-inhibited cells." (PMID 22021332, 2011). "Furthermore, PinX1 inhibition in cancer cells activates telomerase and elongates telomeres, whereas PinX1 overexpression has the opposite effects." (PMID 22021332, 2011). "Moreover, telomere lengthening induced by PinX1 inhibition occurs at most chromosome ends, a feature of cancer cells." (PMID 22021332, 2011). "Moreover, PinX1 inhibition potently increases, whereas PinX1 overexpression suppresses, tumorigenicity of cancer cells." (PMID 22021332, 2011). "Interestingly, overexpression of PinX1 also enhances the sensitivity of human cancer cells to chemotherapy drug 5-fluorouracil." (PMID 22021332, 2011). "An increasing body of evidence suggests that PinX1 is an attractive new target in cancer therapy." (PMID 22021332, 2011). "Thus, the LPTS/PinX1 protein or its active region may have anticancer effects and is expected to be useful for the treatment of cancer." (PMID 40896430, 2025). "Notably, the deletion of PINX1 exhibited a synergistic effect with PARP inhibition in cancer cells." (PMID 39174499, 2024). "However, the ability of PinX1 to alter the biology of cancer cells needed to be further clarified." (PMID 32028978, 2020).